IL6 (interleukin 6)
Diseases named in the same sentence as IL6 in open-access papers (continued):
Sharing a sentence is not in itself a finding about the gene and the disease.
tumor (continued). "In another study, IL-6 was shown to promote the nuclear translocation of β-catenin via the COX-2/PGE2 pathway, thereby inducing EMT and enhancing tumor cell invasion." (PMID 40304000, 2025). "IL6 activates STAT3 signaling, contributing to tumor progression, chemotherapy resistance, and immune evasion.It enhances survival and promotes cell migration." (PMID 40427188, 2025). "For example, persistent IL-6/STAT3 signaling within the tumor microenvironment induces DNMT1 and EZH2 expression, thereby reinforcing the epigenetic repression of tumor suppressor genes and maintaining a pro-oncogenic inflammatory state." (PMID 41226277, 2025). "In dysbiotic mice, macrophages release IL-6, promoting colorectal cancer proliferation and EMT, with macrophage depletion reversing tumor-promoting effects." (PMID 40948759, 2025). "Reactive oxygen species (ROS), nitric oxide (NO), and a spectrum of pro-inflammatory cytokines such as IL-6, TNF, and IFN-γ can exert mutagenic effects on tumor cells and their surrounding microenvironment." (PMID 40821768, 2025). "Inflammatory mediators, such as IL-6, TGF-β, and TNF-α contribute to cancer-related inflammation via the interaction between inflammatory cells and tumor cells." (PMID 41614883, 2025). "These pro-inflammatory cytokines, such as IL-6 and TNF-α, are released by both tumor and host immune cells and initiate a cascade of intracellular signaling pathways that culminate in skeletal muscle degradation and other systemic dysregulation." (PMID 40869331, 2025). "Further enrichment analysis revealed that iCAF enriched chemokines, TGFβ, ECM, IL6 pathway, PDGFRA pathway, inflammatory response, hypoxia, tumor angiogenesis, and VEGF signaling pathway, which are crucial for tumor progression, metastasis, and immune escape." (PMID 40525824, 2025). "In the colon, LPS and other pathogen-associated molecules activate mucosal immune cells to release pro-inflammatory cytokines (e.g., IL-1β, IL-6, TNF-α), creating an environment conducive to tumor promotion." (PMID 41374093, 2025). "Excess white adipose tissue contributes to elevated levels of circulating free fatty acids and adipokines such as leptin, IL-6, and TNF-α, promoting a chronic inflammatory state that supports tumor progression." (PMID 40895542, 2025). "A comprehensive analysis of 23 cytokines and chemokines revealed elevated levels of tumor-derived GM-CSF, IFN-γ, MCP-1 and CXCL1, alongside a decrease in IL-6 and Gal-9, further supporting the enhanced T cell activity observed following LDHC knockdown." (PMID 40108668, 2025). "Our data revealed that CAFs with reduced GATA6/TET1 exhibited decreased secretion of IL-6, VEGF, and TGF-β (p < 0.05 vs. Control 1), critical mediators of angiogenesis and tumor-stroma crosstalk." (PMID 40216762, 2025). "Chronic inflammatory signaling (e.g., IL-6/STAT3) and PI3K/AKT/mTOR activation contribute to an immune-excluded, myeloid-dominant tumor microenvironment (TME) and primary resistance to PD-1." (PMID 41374963, 2025). "IL-6 activates the JAK/STAT3 pathway, supporting cell survival and resistance to apoptosis, while IL-8 aids tumor invasion, and metastasis." (PMID 39861135, 2025). "The primary function of M1 macrophages is to enhance local inflammatory responses and recruit immune cells by secreting pro-inflammatory cytokines such as IL-1, IL-6, IL-12, IL-23, and TNF-α, thereby forming a strong anti-tumor immune defense." (PMID 40438115, 2025). "The interplay between IL-6 and VEGF establishes a pathological axis that amplifies inflammation and vascularization in the tumor microenvironment." (PMID 40433410, 2025). "Protein-array profiling indicated that CXCL12 silencing broadly reduced pro-tumor mediators in CAF-conditioned medium (e.g., IL-6, TGF-β1, VEGF, FGF, EGF, and MCP-1) while increasing anti-angiogenic factors such as serpin B5 and thrombospondin-2." (PMID 41514658, 2025).
tumor (continued). "Interleukin-6 (IL-6) and tumor necrosis factor alpha (TNF-α) induce neutrophilia by promoting the paraneoplastic production of myeloid growth factors by tumor cells." (PMID 40095867, 2025). "The current study, hence, adds details to this established understanding, suggesting that immunomodulation via IL-6 and IDO1 of the tumor microenvironment by MSCs during cisplatin treatment, even at subtoxic doses, is a relevant mechanism to consider." (PMID 40699630, 2025). "Hypoxia, local cytokine gradients (e.g., IL-6, IL-1β), and metabolic stress can all increase TDO expression, affecting immune infiltration and medication penetration in the tumor environment." (PMID 41035912, 2025). "Both PGPs and PGPs-NE markedly improved these parameters, with PGPs-NE showing greater effectiveness in reducing tumor weight, restoring antioxidant levels, and inhibiting the expression of PCNA, MMP-9, and IL-6." (PMID 41307829, 2025). "It has been previously reported that IL-1 beta, IL-6, and IL-8 levels in specimens from OSCC patients directly correlate with the clinical aggressiveness of the tumor." (PMID 40805215, 2025). "elimination of CAFs increases the level of IL-2, IL-7, the number of dendritic and cytotoxic T cells with antitumor functions, and decreases the level of IL-4, IL-6, VEGF, the number of pro-tumor macrophages, and immunosuppressive T lymphocytes." (PMID 40136652, 2025). "IL-6, VEGF, PDGF-BB, IP-10, MCP-1, and IL-9 exhibit complex, often context-dependent functions in tumours, making them potential biomarkers and therapeutic targets." (PMID 40733274, 2025). "IL-6 activates JAK/STAT3 signaling pathway to promote inflammatory responses and support tumor progression." (PMID 40255422, 2025). "Elevated IL-6, commonly found in HNSCC, is known to promote JAK/STAT-dependent tumor cell proliferation." (PMID 40764401, 2025). "Tumor-infiltrating lymphocytes and cancer cells release many inflammatory mediators including VEGF, IL-6, and GM-CSF, which further activities and recruitments immunosuppressive immune cells." (PMID 40796714, 2025). "Additionally, we performed GSEA enrichment analysis using tumor-related phenotypes associated with IL1RAP, which revealed significant enrichment in hallmark pathways such as inflammatory response, TNFA signaling via NFKB, KRAS signaling down, and IL6 JAK-STAT3 signaling via." (PMID 40444099, 2025). "Pro-inflammatory cytokines such as interleukin (IL)-6, IL-1β, IL-8, and tumor necrosis factor-alpha (TNF-α) are frequently upregulated and contribute to tumor cell proliferation, migration, and invasion." (PMID 40612845, 2025). "In CRC, tumor EVs enriched with miR-21-5p similarly engage TLR7 on liver Kupffer cells, inducing them to produce IL-6 and adopt an M2 polarization, thereby establishing an inflammatory, tumor-promoting niche in the liver." (PMID 40574836, 2025). "Inhibition of ER stress (4-PBA) or specifically IRE1α (4μ8C) significantly reduced IL-6 secretion, and findings further corroborated by elevated IRE1α and XBP1s expression in NSCLC tumor tissues from single-cell sequencing data." (PMID 41254082, 2025). "In obese mouse, compared with the contralateral adipose tissue of the tumor, the ipsilateral adipose tissue of the tumor activated the STAT3/NF-κB p65 signal pathway and increased IL6 secretion." (PMID 40841364, 2025). "SASP factors, including IL-6, IL-8, and VEGF, reshape the tumor microenvironment (TME), promoting therapy resistance and metastasis." (PMID 41463272, 2025). "Generation of a DC3-like subset can be achieved by culturing DC2 with IL-6, PGE2, and M-CSF as well as tumor cell supernatant." (PMID 40136707, 2025). "IL15 is involved in immune cell infiltration to tumour sites, and CEBP stimulates Inflammatory marker IL6." (PMID 40434957, 2025). "In the tumor microenvironment, however, both IL-6 and CCL2 predominantly support M2-like TAM polarization, thereby fostering angiogenesis, immune suppression, and tumor progression." (PMID 41310829, 2025).
tumor (continued). "Conversely, B7-H3 upregulation was observed to promote the secretion of IL-2, IL-6, IL-17, and TGF-β1, while concurrently leading to reduced IFN-γ production in T-cells within the tumor microenvironment (TME)." (PMID 40214484, 2025). "Meanwhile, deficiency of circRNA-14,052 led to a significant decrease in circRNA-14,052, IKBKB, IL-6, JAK2, and STAT3 levels, and an increase in miR-214-3p levels in tumor tissues from MCF-7 tumor-bearing mice compared to the LV-NC group." (PMID 41044672, 2025). "In vitro coculture experiments have demonstrated that LSECs and metastatic tumor cells interact via ICAM‐1/LFA‐1, promoting the release of tumor‐derived PGE‐2, IL‐6, VEGF, and MMPs, as well as LSEC‐derived IL‐1β, IL‐6, and TNF‐α into the TME." (PMID 40027151, 2025). "Mounting evidence suggests that the JAK/STAT3 signaling pathway plays a key role in tumor metastasis and EMT, with an active IL6/JAK2/STAT3 axis and stem cell‐like characteristics contributing to the poor prognosis of metastasized breast cancers." (PMID 40874680, 2025). "IL-6, activating the JAK/STAT3 pathway, stimulates inflammatory processes in the tumor microenvironment, which paradoxically support tumor development, promote angiogenesis, and support the adaptation of tumor cells to therapy, including chemotherapy." (PMID 40362280, 2025). "IL-6 and IL-1β can enhance CD274 expression in tumor cells by activating the JAK2/STAT3 signaling pathway, making it difficult to be recognized by T cells and facilitating tumor immune evasion." (PMID 39911394, 2025). "IL-6 and TNF can affect all stages of tumor growth, such as initiation, promotion, progression, and metastasis." (PMID 39802656, 2025). "A large number of cytokines, chemokines, and growth factors secreted by M2-TAMs, including TGF-β, PDGF, IL-6, IL-10, CXCL, COX-2, VEGF, and PDGF, favor angiogenesis and tumor progression." (PMID 40805183, 2025). "As is known, IL-6 functions as the activator of the canonical STAT3 pathway mediating cancer cell proliferation and metastasis as well as the suppressor of tumor immune responses." (PMID 40158127, 2025). "In cancer, MDSCs expand significantly and accumulate in the TME under the influence of tumor-secreted factors such as CSF1, G-CSF, IL-6, and prostaglandins." (PMID 40821795, 2025). "In NSCLC, high tumor-infiltrating Th1 cells correlate with poor prognosis, whereas Th17 dominance in melanoma and CRC promotes immunosuppression through IL-6/STAT3 signaling and regulatory T cell (Treg) conversion." (PMID 40564985, 2025). "Under hypoxic stress, TAMs secrete TNF-α, IL-1, IL-6, IL-8, VEGF, GM-CSF, TGF-β, and MMP, promoting tumor angiogenesis and invasion." (PMID 40231472, 2025). "The FXR agonist obeticholic acid (OCA) induces cell cycle arrest and suppresses tumor cell invasion via STAT3 dephosphorylation and SOCS3 upregulation, concomitant with reduced IL-6/STAT3 signaling and pro-inflammatory cytokine (IL-1β, IL-6) secretion." (PMID 40980688, 2025). "The elevated expression of several cytokines such as IL-1β, IL-6, IL-10, TNF-α, and TGF-β has been reported to be involved in tumor initiation and progression in various types of cancer." (PMID 40722593, 2025). "Leptin also acts as a pro-inflammatory adipokine that induces IL-6 and transforming growth factor β (TGF-β) overexpression and an oncoinflammatory tumor microenvironment development via JAK/STAT3, c-Jun, and Akt pathway activation." (PMID 40227577, 2025). "For instance, STAT3, IL6, and TNF are key inflammatory mediators that activate downstream NF-κB signaling and support a tumor-permissive microenvironment." (PMID 40593037, 2025). "Mechanistically, tmTNF+ neutrophils engage TNFR2 on tumor cells, inducing reciprocal CXCL1/IL-6 upregulation (feedforward loop) and driving iCAF differentiation." (PMID 40948749, 2025).
tumor (continued). "In the tumor context, these exosomes contain immunosuppressive molecules such as TGF-β, IL-10, IL-6, prostaglandin E2 (PGE2), and Foxp3, which can suppress cytotoxic immune responses by disarming CD4+ T-cells, NK cells, and macrophages." (PMID 40427384, 2025). "CAFs can secrete various soluble cytokines and growth factors, including IL-6, TGF - β, and CXCL12, which bind to receptors on tumor cells and activate oncogenic signaling pathways such as JAK/STAT3, PI3K/AKT, and MAPK." (PMID 40959080, 2025). "IL6-induced mtDNA leakage and activation of the cGAS-STING pathway help EC cells evade immune detection, promoting tumor progression." (PMID 39949780, 2025). "MIFs derived from these CD36+ CAFs activate myeloid‐derived suppressor cells (MDSCs) through the IL‐6/STAT‐3 pathway, promoting an immunosuppressive TME and enhancing tumor stem cell capabilities." (PMID 41164803, 2025). "We next quantified pathway-level activity for eight tumour-relevant processes, including epithelial–mesenchymal transition (EMT), angiogenesis, hypoxia, inflammatory response, IL6-JAK-STAT3 signalling, TNFα-NFκB signalling, and interferon responses." (PMID 41007424, 2025). "Given the high level of IL-6 in NSCLC patients, we cultured NSCLC cell lines under hypoxic conditions (1% O2) to better simulate the tumor microenvironment (TME) in vivo in solid tumors." (PMID 41254082, 2025). "EGCG, the primary catechin in green tea, inhibits tumor-promoting pathways by blocking NF-κB and STAT3 activation, thus reducing the transcription of IL-6, MMP-9, and CD44." (PMID 40869364, 2025). "MyD88 was required for induction of IL-6 and TNF-α, activation of MDSCs, and tumor metastasis mediated by tumor-derived exosomes." (PMID 40443670, 2025). "Its activation, driven by tumor-infiltrating microglia and macrophage-derived extracellular factors such as EGF, PDGFB, SDF-1α, IL-6, and IL-8, enhances tumor cell motility and survival." (PMID 40867240, 2025). "On the one hand, inflammatory cells secrete a variety of cytokines and chemokines, such as interleukin-6 (IL-6) and tumor necrosis factor-α (TNF-α), which promote tumor cell proliferation, angiogenesis, and ECM remodeling." (PMID 41142435, 2025). "This inhibitory effect led to a marked decrease in gene expression of pro-inflammatory factors including IL6, IL8 and IL1B, reducing the pro-inflammatory state within tumor microenvironment." (PMID 40535567, 2025). "Immune cells like TAMs, neutrophils, and lymphocytes secrete pro-inflammatory cytokines (e.g., IL-6, TNF-α, IL-1β) that activate NF-κB and STAT3 signaling, enhancing tumor proliferation, survival, and metastasis." (PMID 41311372, 2025). "This suggests that the deficiency of miR-214-3p mediates the upregulation of IKBKB, which subsequently activates IL6/JAK/STAT3 signaling, thereby promoting tumor progression." (PMID 41044672, 2025). "Polarization to N1 (anti-tumor, IFNβ/IL-1β-driven) or N2 (pro-tumor, TGF-β/IL-6/7/8-driven) phenotypes influences tumor dynamics." (PMID 40242773, 2025). "Thirdly, CAFs are instrumental in mediating immunosuppression within the tumor microenvironment by secreting factors such as TGF-β and IL-6, which modulate immune cell function and contribute to immune evasion by the tumor." (PMID 40313969, 2025). "These conditions can promote pro-inflammatory cytokine release (IL-1β, IL-6 and TNF-α), angiogenesis and tumor proliferation." (PMID 41395614, 2025). "For example, CAFs secreted IL-6, CXCL12, and MCP-1 promote the polarization of tumor-related macrophages toward the tumor-promoting phenotype M2, thereby impairing effector T cell responses and inducing immunosuppression." (PMID 40296919, 2025). "TAM-derived cytokines such as IL-6 and TNF-α activate signaling pathways like STAT3 and NF-κB in tumor cells, inducing EMT and increasing metastatic potential." (PMID 41280929, 2025).
tumor (continued). "It is clear that neutrophils (a) play a predominantly immunosuppressive, tumor trophic role in UBC and (b) that excess IL-6 is one of the drivers of that." (PMID 40149682, 2025). "NO also affects the immune environment of the tumor: it promotes the secretion of cytokines (TNF-α, IL-6, IL-8), reprograms macrophages to an M2 phenotype, and promotes T-reg expansion, leading to tumor immunotolerance." (PMID 40649317, 2025). "IL-1β and IL-6, regulated by JAK/STAT and NF-κB signaling, promote tumor proliferation and immune evasion, while IL-10 and TGF-β drive M2 macrophage polarization and Treg expansion, fostering an immunosuppressive tumor milieu." (PMID 40076502, 2025). "IL-6, for instance, activates the JAK/SSTAT3 signaling pathway, which is critical for promoting CK19 transcription and sustaining tumor-cell proliferation and invasiveness." (PMID 40699634, 2025). "M1 macrophages exhibit a strong pro-inflammatory profile, secreting cytokines such as TNF-α, IL-1β, and IL-6, thereby activating additional immune cells, especially CD8+ T cells, and enhancing tumor immune surveillance." (PMID 40475760, 2025). "Several CAF-derived chemokines such as CCL2, CCL26, IL6, CXCL1, and CXCL8 mediate tumor progression, angiogenesis, and drug resistance, suggesting that tumor–CAF crosstalk is a bidirectional, dynamic, and adaptive process." (PMID 40447617, 2025). "This shift is characterized by the up-regulation of pro-inflammatory cytokines such as IL-6 and TNF-α, which have anti-tumor properties, and the down-regulation of immunosuppressive cytokines such as IL-10 and TGF-β." (PMID 40507156, 2025). "Tumor-associated macrophages (TAMs), along with cytokines such as IL-1β, IL-6, and transforming growth factor-β (TGF-β), contribute to the establishment of a highly immunosuppressive and tumor-promoting niche." (PMID 40881678, 2025). "Mechanistically, increased neutrophil counts reflect a pro-tumorigenic inflammatory state driven by cytokines such as IL-6 and VEGF, while decreased lymphocyte levels indicate compromised anti-tumor immunity." (PMID 41180708, 2025). "In vivo, C26 tumor-bearing mice showed an increase in circulating LIF that preceded and exceeded the increase in IL-6." (PMID 40869331, 2025). "CAFs deposit new matrix proteins (e.g., collagens and fibronectin) and secrete growth factors (TGF-β, VEGF, PDGF, FGF2, and HGF) and cytokines (IL-6, IL-8, and CXCL12/SDF-1) that jointly reprogram the matrix and tumor behavior." (PMID 41409250, 2025). "Additional analysis of the tumor microenvironment based on the expression of CD8+ T and PD-L1 showed that the high Compared to the low IL-6 group, the IL-6 group had a reduced percentage of type I (PD-L1+TILs+) tumors (P=0.012)." (PMID 40433391, 2025). "IL-6 and TNF-α promote tumor progression by enhancing inflammation and creating an immunosuppressive microenvironment, while MCP-1 recruits monocytes and macrophages, potentially aiding immune evasion and metastasis." (PMID 40171218, 2025). "M2-polarized TAMs dominate the immunosuppressive tumor microenvironment (TME) and promote EMT through cytokines such as TGF-β, IL-6, and CCL2." (PMID 40304000, 2025). "Together, these findings suggested that both IL-6 and EBV DNA levels influence tumor cells directly or indirectly by promoting an immunosuppressive milieu and treatment resistance, which ultimately hampered the efficacy of chemoimmunotherapy." (PMID 40160826, 2025). "Mechanistically, IL-6 activates the JAK2/STAT3 signaling pathway, which promotes EMT in SACC, thereby forming PMN to facilitate tumor metastasis." (PMID 39935427, 2025). "CAFs contribute to tumor progression by releasing cytokines such as TGF-β, IL-6, and IL-8, which promote proliferation, migration, immune evasion, and epithelial-mesenchymal transition (EMT)." (PMID 41311372, 2025).